SEMA6D (semaphorin 6D)
Description:
Shows growth cone collapsing activity on dorsal root ganglion (DRG) neurons in vitro. May be a stop signal for the DRG neurons in their target areas, and possibly also for other neurons. May also be involved in the maintenance and remodeling of neuronal connections. Ligand of TREM2 with PLXNA1 as coreceptor in dendritic cells, plays a role in the generation of immune responses and skeletal homeostasis (By similarity).
Synonyms: KIAA1479; FLJ11598
Tractability: Antibody: its Gene Ontology location is reachable by antibodies, with high confidence; UniProt places it where antibodies can reach, with medium confidence; UniProt predicts a signal peptide or a membrane-spanning region; the Human Protein Atlas places it where antibodies can reach. PROTAC: ubiquitination databases record sites on it; its protein half-life has been measured.
Gene: Protein-coding gene on chromosome 15 (47,184,101 to 47,774,228, forward strand). Ensembl gene ENSG00000137872.
Subcellular location: Cell membrane (Isoform 1); Cell membrane (Isoform 2); Cell membrane (Isoform 3); Cell membrane (Isoform 4); Cell membrane (Isoform 5); Cytoplasm (Isoform 7)
Subcellular location (Human Protein Atlas): Plasma membrane; Golgi apparatus
Pathways (Reactome):
Developmental Biology: Other semaphorin interactions
Gene Ontology:
Molecular function: chemorepellent activity; receptor ligand activity; semaphorin receptor binding
Biological process: axon guidance; neural crest cell migration; positive regulation of cell migration; semaphorin-plexin signaling pathway; T cell activation via T cell receptor contact with antigen bound to MHC molecule on antigen presenting cell; negative chemotaxis
Cellular component: plasma membrane; cytoplasm
Genetic constraint (gnomAD): Loss-of-function variants: 27 observed, 94.07 expected, observed/expected ratio (o/e) 0.29, 90% interval 0.21 to 0.4. The upper end of that interval is the gene's LOEUF score, 0.4, which puts it in group 1 of 6, group 1 being the genes least tolerant of losing a copy. Missense variants: 1,102 observed, 1,316.5 expected, observed/expected ratio (o/e) 0.84, 90% interval 0.8 to 0.88. Synonymous variants: 468 observed, 481.29 expected, observed/expected ratio (o/e) 0.97, 90% interval 0.9 to 1.05.
Homologues: Orthologues: chimpanzee SEMA6D (99% identical), macaque SEMA6D (99% identical), pig SEMA6D (97% identical), dog SEMA6D (97% identical), rabbit SEMA6D (97% identical), mouse Sema6d (95% identical), rat Sema6d (95% identical), guinea pig SEMA6D (94% identical), tropical clawed frog sema6d (82% identical), zebrafish sema6d (69% identical). Paralogues in human: SEMA6A (44% identical), SEMA6C (36% identical), SEMA6B (35% identical), SEMA5B (20% identical), SEMA3D (20% identical), SEMA4D (20% identical), SEMA4C (19% identical), SEMA5A (19% identical), SEMA3A (19% identical), SEMA3B (19% identical), SEMA4B (19% identical), SEMA3E (19% identical), and 7 more.
Diseases named in the same sentence as SEMA6D in open-access papers:
SEMA6D is named in the same sentence as 32 diseases in open-access papers, as found by Europe PMC text mining. Sharing a sentence is not in itself a finding about the gene and the disease. The quoted sentences say what the papers report.
breast carcinoma (11 papers, 2013 to 2025). "It has been discovered that treatment resistance in breast cancer is linked to the upregulation of the common target gene Semaphorin 6D (SEMA6D) and the high expression of miR-195 and miR-26b." (PMID 38792263, 2024). "The high expression of miR-195 and miR-26b and down-regulation of their common target gene Semaphorin 6D (SEMA6D) were found to be associated with therapy resistance in breast cancer and, thus, this signaling axis is suggested as a predictive marker for chemotherapy response." (PMID 37568568, 2023). "SEMA6D regulates the proliferation, migration and invasion of breast cancer cell lines through the EMT." (PMID 41259456, 2025). "Semaphorin-6D is involved in cell development and migration as a guiding factor in head and neck, lung, and breast cancers." (PMID 40265010, 2025). "For instance, SEMA6D overexpression in human breast cancer cell lines upregulated the expression of genes related to the cell cycle and epithelial-mesenchymal transition, leading to increased malignant characteristics such as migration and invasion." (PMID 38329122, 2024). "One example is miRNA-195 which was found to induce resistance to chemotherapy in breast cancer by reducing the levels of a protein known as SEMA6D." (PMID 37108278, 2023). "We show that microRNA-195 and microRNA-26b induce resistance to chemotherapy in breast cancer by reducing the levels of the protein SEMA6D." (PMID 34885090, 2021). "Although the issue of different isoforms isan intriguing one, to date there is no data on the functional importanceof different SEMA6D isoforms in breast cancer, and it requires furtherresearch." (PMID 35571788, 2022).
osteosarcoma (7 papers, 2016 to 2023). A usually aggressive malignant bone-forming mesenchymal neoplasm, predominantly affecting adolescents and young adults. "SEMA6D (Semaphorin 6D) encodes a transmembrane protein and its overexpression increases proliferation and tumor formation, playing an oncogene role in osteosarcoma." (PMID 29854292, 2018). "Several oncogenes, including SEMA4D and SEMA6D, have been involved in axon guidance in human osteosarcomas." (PMID 36408691, 2023). "It has been shown that miR-506-3p reduced cisplatin resistance via CircUBAP2/SEMA6D/miR-506-3p axis that affects the Wnt signaling in osteosarcoma (OS) cells." (PMID 37051101, 2023). "Accordingly, SEMA4D and SEMA6D have been identified as proto-oncogenes in human osteosarcoma cells, and their expression was found to be highly elevated in comparison to normal human osteoblasts." (PMID 38067240, 2023). "CircRNA UBAP2 increased the expression of Sema6D in osteosarcoma cells and led to cisplatin resistance via sponging miR-506-3p." (PMID 33621206, 2021). "Collectively, the study demonstrated that high expression of circUBAP2 and SEMA6D promotes the Wnt/β-catenin signaling pathway and cisplatin resistance, while the microRNA miR-506-3p negatively regulates circUBAP2 and SEMA6D and restrains osteosarcoma invasiveness." (PMID 38067240, 2023).
gastric cancer (4 papers, 2018 to 2024). A primary or metastatic malignant neoplasm involving the stomach. "As part of the SEMA family, Sema6D comes in four forms, of which Sema6D is known to be associated with the development and occurrence of non-small cell lung cancer, gastric cancer, and osteoma." (PMID 40777970, 2024). "Furthermore, a 2016 study using samples of human gastric cancer tissues has also shown an increased prevalence of Sema6D and Plexin A1 in endothelial vascular cells and an association of Sema6D and plexin-A1 with VEGFR2." (PMID 38375479, 2024). "The study also demonstrated that patients with gastric cancer with deeper cancer invasion, worse differentiation, and higher clinical stage had higher Sema6D levels in their cancer tissues." (PMID 40777970, 2024). "As a result of silencing Sema6D in gastric cancer patients, ERK signaling pathway protein expression was reduced, inhibiting the proliferation, migration, and invasion of gastric cancer cells." (PMID 40777970, 2024). "In models of gastric cancer, signaling due to Sema6D and Plexin-A1/VEGFR2 interaction results in effects similar to VEGF binding alone." (PMID 32210960, 2020). "Poor prognosis of gastric cancer has been correlated with Sema6D expression and increased angiogenesis." (PMID 32210960, 2020). "SEMA6D has been reported to be highly expressed in vascular epithelial cells in gastric cancer; it was also positively correlated with the expression of vascular endothelial growth factor receptor 2 (VEGFR2)." (PMID 29507648, 2018). "In summary, the Sema6D expression level can affect the biological behavior of gastric cancer cells." (PMID 40777970, 2024). "SEMA6D expression was knocked down in human gastric cancer cells using RNA interference technology." (PMID 40777970, 2024). "The Sema6D protein assay results showed that the Sema6D protein level in human gastric cancer cells SGC-7901 (mean of si-NC, si-1, si-2 groups) was higher than that in human gastric epithelial cells GES-1, and the difference was statistically significant (P < 0.05)." (PMID 40777970, 2024). "That down-regulation of Sema6D expression level can weaken ERK and PI3K/AKT/mTOR signaling pathways and thus inhibit gastric cancer cell proliferation, migration, and invasion." (PMID 40777970, 2024). "Given this, we speculate that the Sema6D expression level may affect the activation level of ERK and PI3K/AKT/mTOR signaling pathways in gastric cancer patients, thus affecting the proliferation and migration ability of gastric cancer cells." (PMID 40777970, 2024). "Knockdown of Sema6D can down-regulate ERK, PI3K/AKT/mTOR signaling pathway-related protein expression and inhibit the proliferation, migration and invasion of gastric cancer cells, which is expected to be an effective target for gastric cancer drug development and has clinical research value." (PMID 40777970, 2024).
asthma (2 papers, 2022). "Concerning pathological condition of asthma, blockage of Sema6D signal from the tissue niches might have therapeutic potential of attenuating airway type 2 inflammation by up-regulating IL-10 production from ILC2s." (PMID 36038260, 2022). "Interestingly, five of these loci, i.e., ACTN1, PDS5B, SEMA6D, SPRY4, and TENM3, have been reported of association with the genetic susceptibility of asthma." (PMID 36051697, 2022).
colitis (2 papers, 2021 to 2024). Inflammation of the colon. "There is evidence of the anti-inflammatory activity of SEMA6D mediating M2 macrophage polarization in mice, and its deficiency predisposes colitis development." (PMID 39596507, 2024).
lung carcinoma (2 papers, 2022 to 2024). "SEMA6D (Semaphorin 6D) was found to be associated with parental longevity and lung carcinoma in previous GWAS." (PMID 35624665, 2022). "To investigate the function of Sema6D in the TME, we initially subcutaneously injected B16F10 melanoma and KP lung cancer cell lines into WT and Sema6d-KO mice." (PMID 38329122, 2024).
autoimmune conditions (1 paper, 2017). "Novel gene-longevity associations included genes MICA/B (a locus previously linked to autoimmune conditions rheumatoid arthritis and multiple sclerosis), TOX, ZW10, SEMA6D, EGLN2/CYP2A6, EXOC3L2/MARK4 and C20orf187." (PMID 29227965, 2017).
bladder cancer (1 paper, 2024). "In this study, we investigated for the first time the role of sema6D in bladder cancer." (PMID 39061999, 2024). "Considering we found higher urinary sema6D in bladder cancer patients and the observations of other scientists about the roles of semaphorins in this neoplasm, we may suspect that it promotes the development of bladder tumor; however, this requires more in-depth research." (PMID 39061999, 2024). "To date, the role of semaphorin 6D in bladder cancer has never been studied." (PMID 39061999, 2024).
colorectal cancer (1 paper, 2018). A primary or metastatic malignant neoplasm that affects the colon or rectum. "The methylation of five genes (AHCYL2, IL11RA, SEMA6D, BIRC3, and HADHB) was associated with tumors, and four genes (IL11RA, CHL1, SEMA6D, and BIRC3) were associated with colorectal cancer." (PMID 29507648, 2018).
COVID-19 (1 paper, 2025). A disease caused by infection with severe acute respiratory syndrome coronavirus 2. "By 6 weeks post-inclusion, COVID-19 hypermethylation of genes with the highest fold-change compared to healthy controls included FAM178B, FYN, TMCC1, TMEM212-AS1, and FIG4, while the top five hypomethylated genes were GIT2, PDGFRB, SEMA6D, TNFAIP8, and ETV6." (PMID 41227320, 2025).
hypothyroidism (1 paper, 2012). Abnormally low levels of thyroid hormone. "Her deletion comprises 19 genes and predicted genes including FBN1, besides SEMA6D and COPS2 that may have contributed to the intellectual deficit and hypothyroidism, respectively." (PMID 22260333, 2012).
language disorder (1 paper, 2024). A category of disorders characterized by an impairment in the development of an individual's language capabilities, which is in contrast to his/her non-verbal intellect. "The genes SEMA6D, AUT2 and ROBO1, OXR1 and MUC6 were reported as interesting candidate genes because potential pathogenic variants co-segregated with the language disorder in affected relatives of the respective probands." (PMID 38298611, 2024).
oral carcinoma (1 paper, 2024). "Since the MOC2 oral cancer model showed that Sema6d-KO mice exhibited greater CD8+ T cell infiltration in the TME than WT mice, we treated both groups of mice with a PD-1–blocking antibody." (PMID 38329122, 2024). "Here, we discovered that Sema6d deficiency suppressed tumor progression via increased cytotoxic CD8+ T cell infiltration into tumors in a murine oral cancer model using MOC2 cells without endogenous Sema6d expression." (PMID 38329122, 2024). "Furthermore, we analyzed public scRNA-seq data from patients with oral cancer and found that SEMA6D was mainly expressed by nonhematopoietic cells in the TME." (PMID 38329122, 2024).
Parkinson disease (1 paper, 2013). A progressive degenerative disorder of the central nervous system characterized by loss of dopamine producing neurons in the substantia nigra and the presence of Lewy bodies in the substantia nigra and locus coeruleus. "The gene expression of the extra-cellular ligand SEMA6D, proposed as one of three initiators of the integrated Parkinson's disease mechanism, was found in our miRNA regulatory network to be regulated by seven miRNAs (miR-124-1, miR-128-1, miR-16-1, miR-19a, miR-23b, miR-30a and miR-9)." (PMID 24688734, 2013).
restless legs syndrome (1 paper, 2017). A condition that occurs while resting or lying in bed; it is characterized by an irresistible urgency to move the legs to obtain relief from a strange and uncomfortable sensation in the legs. "The BI-ENRICH algorithm showed that most of the top pathways identified for restless legs syndrome were related to neurodevelopment, including neurogenesis (genes MDGA1, MYT1, NTNG1, and SEMA6D), cell-junction organisation (PKP4 and SMAD3), and axon guidance (NTNG1 and SEMA6D)." (PMID 29029846, 2017).
skin tumors (1 paper, 2021). "Along the same lines, we also highlight activinβA (Inhba) because this member of the TGF-β superfamily was shown to increase malignancy and metastatic spread of skin tumors; semaphorins (Sema6d, Sema4d), which can shape the tumor microenvironment; and ligands of the EGF receptor (Areg, Ereg)." (PMID 33497366, 2021).
triple-negative breast carcinoma (1 paper, 2015). An invasive breast carcinoma which is negative for expression of estrogen receptor (ER), progesterone receptor (PR), and human epidermal growth factor receptor 2 (HER2). "The expression of SEMA6D gene may play an important role in promoting patient survival, especially among triple negative breast cancer (TNBC) patients." (PMID 25973277, 2015). "The expression of SEMA6D gene may play an important role in promoting patient survival, especially among triple negative breast cancer patients." (PMID 25973277, 2015).
tumor (17 papers, 2017 to 2026). "An in vivo study indicated that Sema6d-overexpressing MOC2 cells were associated with significantly reduced tumor infiltration of CD8+ T cells compared with control MOC2 cells." (PMID 38329122, 2024). "The process of polarizing anti-inflammatory macrophages, in which SEMA6D plays a crucial role, as demonstrated both in vitro and in vivo, holds potential implications for understanding the function of tumor-associated macrophages (TAMs)." (PMID 38067240, 2023). "Several semaphorins including Sema3a, Sema3f, Sema3g and Sema6a have been reported to exert tumor growth-inhibiting activities while several others such as Sema4d and Sema6d have been associated with tumor-promoting functions in various cancer types." (PMID 35223842, 2022). "Although SEMA6D expression has been associated with tumor progression and angiogenesis in gastric cancer, a specific role in the regulation of tumor-associated inflammation has not been investigated." (PMID 30658382, 2019). "Sema6D may seem to be associated with the tumor origin in the lateral wall of the bladder; however, that should be further studied on larger cohorts." (PMID 39061999, 2024). "Collectively, our findings establish SEMA6D as a crucial tumor suppressor epigenetically silenced in CRC." (PMID 41735257, 2026). "This study identified Semaphorin 6D (SEMA6D) as a potential tumor suppressor that was markedly underexpressed in CRC and associated with poor prognosis." (PMID 41735257, 2026). "To further investigate the mechanism of immunosuppression by Sema6D, we isolated T cells from tumor-draining LNs and stimulated them with anti-CD3/anti-CD28 antibodies with or without rSema6D." (PMID 38329122, 2024). "IHC analysis showed that the frequency of tumor-infiltrating CD8+ cells was significantly elevated in Sema6d-KO mice compared with WT mice." (PMID 38329122, 2024). "Compared with WT mice, Sema6d-KO mice showed significantly slower tumor growth and a significantly higher number of tumor-infiltrating CD8+ T cells and OVA-tetramer+CD8+ T cells." (PMID 38329122, 2024). "Although LN metastases were significantly more frequent in WT mice compared with Sema6d-KO mice, the metastases were more influenced by primary tumor size than by Sema6d expression." (PMID 38329122, 2024). "Tumor progression was significantly reduced in Sema6d-KO mice compared with WT mice, due to increased tumor-infiltrating CD8+ T cells." (PMID 38329122, 2024). "Tumor progression was significantly decreased in Sema6d-knockout (Sema6d-KO) mice compared with wild-type (WT) control mice." (PMID 38329122, 2024). "The tumor growth curve and survival data indicated that tumor growth in Sema6d-KO mice was much slower than that in WT mice." (PMID 38329122, 2024). "Taken together, these reports highlight the substantial role of SEMA6D in the tumor microenvironment and suggest the SEMA6D/VEGF(R) axis as a possible target for pharmacological intervention." (PMID 38067240, 2023). "Taken together, our study demonstrates that IL-17C promotes tumor angiogenesis through VEGF production via a STAT3/miR-23a-3p/SEMA6D axis, suggesting its potential as a novel target for anti-CRC therapy." (PMID 32492770, 2020). "An ex vivo experiment using T cells from tumor-draining lymph nodes (LNs) demonstrated that recombinant Sema6D (rSema6D) inhibited T cell activation and proliferation induced by anti-CD3/anti-CD28 stimulation, and this inhibitory effect was partially decreased in Plxna4-KO T cells." (PMID 38329122, 2024). "CD8 depletion eliminated the differences in tumor growth between WT mice and Sema6d-KO mice." (PMID 38329122, 2024). "MOC2 cells, which do not express endogenous Sema6d, caused significantly slower tumor progression in Sema6d-KO mice compared with WT mice." (PMID 38329122, 2024). "We analyzed if sema6D concentration is associated with the tumor stage, but we did not observe any correlation, either for plasma or for urinary sema6D." (PMID 39061999, 2024).